DSCR4 (Down syndrome critical region 4)
Synonyms: DCRB; DSCRB
Gene: Long non-coding RNA gene on chromosome 21 (37,951,425 to 38,121,360, reverse strand). Ensembl gene ENSG00000184029.
Diseases named in the same sentence as DSCR4 in open-access papers:
DSCR4 is named in the same sentence as 1 disease in open-access papers, as found by Europe PMC text mining. Sharing a sentence is not in itself a finding about the gene and the disease. The quoted sentences say what the papers report.
Down syndrome (4 papers, 2013 to 2021). "None of the enriched sets of pathways and functions associated with SCN1A was associated with the Down syndrome genes (DYRK1A, PSMG1, RCAN1, DSCR3, DSCR4) or with TSC2." (PMID 29518120, 2018). "For example, in Tc1 mouse livers, the bidirectional promoter of the Down’s Syndrome critical regions 4 and 8 (DSCR4 and DSCR8) is bound by Pol II, enriched for H3K4me3, and generates poly(A) transcripts." (PMID 23246434, 2013). "Further functional analysis of DSCR4 might lead to better understanding of the genomic pathways involved in development of higher brain functions shared by Hominidae members and affected in Down syndrome." (PMID 27289096, 2016).